CXCR4 (C-X-C motif chemokine receptor 4)
Diseases named in the same sentence as CXCR4 in open-access papers (continued):
Sharing a sentence is not in itself a finding about the gene and the disease.
non-small cell lung carcinoma (74 papers, 2005 to 2025). A group of at least three distinct histological types of lung cancer, including non-small cell squamous cell carcinoma, adenocarcinoma, and large cell carcinoma. "A more direct evaluation of the role that the CXCL12 axis plays in chemoresistance indicates that the upregulation of CXCR4 in non-small cell lung carcinoma (NSCLC) mediates Gefitinib-resistance associated with EMT." (PMID 33363463, 2020). "CXCR4 expression is associated with the metastasis of human non-small cell lung cancer (NSCLC), and contributes to breast cancer metastasis." (PMID 30934773, 2019). "By contrast, another study reported that nuclear CXCR4 was associated with a better outcome in patients with non-small-cell lung cancers." (PMID 24659999, 2014). "Strong CXCR4 nuclear staining was associated with significantly better outcome in early-stage non-small-cell lung cancer (NSCLC)." (PMID 24658065, 2014). "Additionally, C-X-C chemokine receptor type 4 (CXCR4) expression on circulating pan-cytokeratin-positive cells was shown to be associated with survival in patients with advanced non-small-cell lung cancer." (PMID 38398206, 2024). "included 140 operable non-small cell lung cancer patients and found that high CXCR4 expression correlated with worse patient outcomes using immunohistochemical methods." (PMID 40607416, 2025). "Extensive research and multiple meta-analyses have explored the multifaceted roles of the chemokine receptor CXCR4 in non-small cell lung cancer (NSCLC), identifying it as a key player in several tumor-promoting processes." (PMID 41149503, 2025). "Expression of CXCR4 is high in non-small cell lung cancer (NSCLC) and small cell lung cancer (SCLC) and has been correlated with aggressive tumor behavior increased metastatic spread to the bone marrow, the liver, and the brain, and poor overall survival." (PMID 41383468, 2025). "Investigations have revealed that the presence of CXCL12 and its receptor CXCR4 in non-small cell lung cancer correlates with tumor development, infiltration, and metastasis." (PMID 40243586, 2025). "In the present study, we investigated the expression of JUNB and CXCR4 in circulating tumor cells (CTCs) of non-small-cell lung cancer and small-cell lung cancer patients and determined their clinical significance." (PMID 36612166, 2022). "EGF was shown to induce the expression of CXC Chemokine Receptor 4 (CXCR4) and promote migration in normoxic non-small cell lung cancer (NSCLC) cells via HIF-1α and the PI3K/AKT and mTOR pathways." (PMID 35158804, 2022). "Overexpression of the cytokine receptor CXCR4 is associated with poor outcomes in stage IV non-small cell lung cancer (NSCLC), with shorter survival in females with high CXCR4 expression." (PMID 33507926, 2021). "Zhang and his colleagues found that circFGFR1 upregulates the expression of CXCR4, the miR-381-3p target gene, to promote the progression of non-small cell lung cancer by miR-381-3p." (PMID 34733854, 2021). "Differential expression of CXCR4 has been reported to be related to the metastatic potential of non-small cell lung cancer (NSCLC)." (PMID 32457792, 2020). "CXCR4+ non-small cell lung cancer (NSCLC) cells are strong examples of tumorigenic stem-like cancer cells that maintain stemness through the CXCR4-mediated STAT3 pathway." (PMID 31752959, 2019). "For example, CXCR4 is upregulated in gefitinib-resistant non-small cell lung cancer cells and promotes epithelial-mesenchymal transition (EMT) and self-renewal activity." (PMID 23442791, 2013). "High levels of CXCR4 expression (> 90%) on CK+PBMCs were also observed by other authors in small pilot studies involving patients with non-small cell lung cancer or patients with metastatic renal cancer." (PMID 22433180, 2012). "Spano demonstrated that nuclear CXCR4 expression represents a better outcome in patients afflicted with non-small-cell lung cancer." (PMID 20181250, 2010).
non-small cell lung carcinoma (continued). "The CXC chemokine, CXCL12, and its receptor, CXCR4 promote metastases of a variety of solid tumors including non-small cell lung cancer (NSCLC)." (PMID 19563666, 2009). "More recently, we showed that both EGF and hypoxia can induce CXCR4 expression in non-small cell lung cancer (NSCLC) cells via the VHL/HIF-1α axis and this process is regulated by both the PI3-kinase/PTEN/AKT/mTor pathway and hypoxia." (PMID 17083723, 2006). "However, studies on CXCR4 in non-small cell lung cancer (NSCLC) tumor immune microenvironment, including those determining its immune efficacy and prognostic potential, are still scarce." (PMID 36308553, 2023). "In recent years, CXCR4, which belongs to the family of chemokines, has been reported to be overexpressed and to play an important role in the cell proliferation, migration, and metastasis of several cancers, including non-small cell lung cancer." (PMID 30103827, 2018). "In addition, non-small cell lung cancer cells with knocked down CXCR4 expression produced larger and more distant tumors compared with wild-type cells, indicating that CXCR4 mediates the metastatic behavior of non-small cell lung cancer." (PMID 26622806, 2015). "Furthermore, a significant correlation with poor OS was obvious in non-small cell lung cancer patients (HR 1.59, 95% CI 1.40–1.81) and in patients showing CXCR4 expression in the cytoplasm (HR 2.10, 95% CI 1.55–2.84) and the membrane (HR 1.74, 95% CI 1.24–2.45)." (PMID 35729596, 2022). "Given that CXCR4 mediates the trafficking of breast and non-small cell lung cancer cells in an organ-specific manner, we hypothesized that there would be an increase in the number of RCC cells in circulation in patients with mRCC, and that these cells would express CXCR4." (PMID 17083723, 2006). "In non-small cell lung cancer (NSCLC), oestradiol activates the epidermal growth factor receptor (EGFR) pathway and stimulates CXCR4 expression, which promote proliferation, angiogenesis, cell migration, and metastasis." (PMID 40164824, 2025). "In non-small cell lung cancer (NSCLC), circFGFR1 acts as a competitive endogenous RNA for miR-381-3p and regulates the expression of CXCR4." (PMID 40458727, 2025). "It was found that ABCB1, CXCR4, and FAK were overexpressed in non-small cell lung cancer (NSCLC) patients and cell lines." (PMID 37749625, 2023). "After using a new CXCR4 inhibitor peptide R, the expression of CD73, CD38, and IL-10 in non-small cell lung cancer is reduced, which can rescue the cytotoxic activity of T cells and prevent TAM polarization." (PMID 35592338, 2022). "In non-small-cell lung cancer (NSCLC), a subset of CD133/CXCR4+ cancer stem cell (CSCs) has been demonstrated to initiate bone metastases." (PMID 35563517, 2022). "Interestingly, C-X-C chemokine receptor type 4 (CXCR4), a receptor widely reported to regulate extramedullary myeloma, was found to induce VCAM1 secretion in non-small cell lung cancer via the regulation of the metalloproteinase, ADAM17." (PMID 37568580, 2023). "It is supposed that NOX1 could mediate the expression of C-X-C chemokine receptor type 4 (CXCR4) and Matrix metallopeptidase 9 (MMP9), which play an important role in the metastasis of non-small-cell lung carcinoma (NSCLC)." (PMID 34205998, 2021). "Signaling between the chemokine receptor CXCR4 and its ligand SDF-1, otherwise known as chemokine ligand (CXCL)-12, contributes to tumor growth, angiogenesis, invasion and metastases in several solid tumors, including non-small cell lung cancer." (PMID 25775124, 2015). "As an example of this hypothesis, it is proposed to combine already marketed targeted therapy drugs against VEGFRs, EGFR, CXCR4 and COX2 in an oncology trial for non-small cell lung cancer patients without further treatment options." (PMID 23877481, 2013).
pulmonary fibrosis (69 papers, 2008 to 2026). Chronic progressive interstitial lung disorder characterized by the replacement of the lung tissue by connective tissue, leading to progressive dyspnea, respiratory failure, or right heart failure. "Modulation of chemokine CXCL12 and its receptor CXCR4 has been implicated in attenuation of bleomycin (BLM)-induced pulmonary fibrosis and carbon tetrachloride (CCl4)-induced hepatic injury." (PMID 26998906, 2016). "The downstream SDF1/CXCR4 axis also converges and accumulates inflammatory cells (neutrophils, monocytes and lymphocytes) into local tissues and regulates the release of inflammatory factors that elicit an inflammatory response and is associated with late lung fibrosis." (PMID 40710342, 2025). "PFOB-NE enhance pulmonary siRNA delivery, effectively silencing STAT3/CXCR4 and inhibiting lung fibrosis progression." (PMID 41480009, 2026). "The anti-CXCR4 i-body AD-114 was developed and demonstrated to have anti-fibrotic activity in a mouse model of pulmonary fibrosis, and in one of our previous studies, we demonstrated the anti-fibrotic effect of i-body AD-114 in an FA-induced CKD model." (PMID 39684834, 2024). "The mTOR inhibitor, sirolimus, inhibits fibrocyte CXCR4 expression, reducing fibrocyte traffic and attenuating lung fibrosis in animal models." (PMID 36853800, 2023). "The addition of G-CSF increases homing to lungs and expression of CXCR4, attenuating lung fibrosis, while pretreatment with N-acetylcysteine enhances intracellular glutathione levels and antioxidant activity." (PMID 38203718, 2023). "Recent studies showed that CXCR4+ macrophage cells were increased in the lung tissue of IPF, indicating that CXCR4+ macrophage infiltration in lung tissues plays an important role in pulmonary fibrosis." (PMID 36915092, 2023). "The results show that the polycation/siRNA/PFOB nanoemulsions are capable of efficiently silencing the expression of STAT3 and inhibiting chemokine receptor CXCR4—two validated targets in pulmonary fibrosis." (PMID 34994102, 2022). "The EPs show deep lung penetration and cytosolic siRNA delivery to mediate highly effective pulmonary STAT3 silencing and CXCR4 inhibition in a mouse model of pulmonary fibrosis upon intratracheal administration." (PMID 34994102, 2022). "Prior studies have shown increased infiltrating mast cell numbers and tryptase activity in human IPF, and therapeutic targeting of CXCL12/CXCR4 signaling attenuated bleomycin induced lung fibrosis in mice." (PMID 34689792, 2021). "We demonstrated that the CXCR4 expression appeared late, and that result, i.e., expression of the CXCR7/CXCR4 axis, shows a causal relationship with pulmonary fibrosis development." (PMID 34082837, 2021). "AMD3100, a specific antagonist for CXCR4, directly inhibits the migration of human fibrocytes and suppressed pulmonary fibrosis formation treated with BLM." (PMID 34082837, 2021). "The mobilization of circulatory fibrocytes and BM-derived primordial germ cells into injured lungs is controlled by the CXCL12/CXCR4 axis promoting the pathogenesis of pulmonary fibrosis." (PMID 34082837, 2021). "Previous studies examined the role of the CXCL12/CXCR4 system in lung fibrosis and demonstrated an essential role in fibrosis development, although the detailed mechanisms remain to be clarified." (PMID 32708315, 2020). "Inhibition of the CXCL12/CXCR4 axis by neutralizing antibodies reduces the development of lung fibrosis through regulation of pro-fibrotic monocyte recruitment." (PMID 32708315, 2020). "Recently, less cytotoxic, more potent, and stable CXCR4 inhibitors such as BL8040 and LY2510924 have been developed, and thus the effects of targeting the CXCL12/CXCR4 axis by CXCR4 inhibitors for the treatment of lung fibrosis should desirably be re-examined." (PMID 32708315, 2020).
pulmonary fibrosis (continued). "In a previous study, the i-body CXCR4 antagonist, AD-114, reduced experimental lung fibrosis and decreased IPF lung fibroblast invasion in-vitro, which supports the targeting of CXCR4 as a therapeutic option in IPF." (PMID 32843095, 2020). "Relatively few studies have examined the contribution of CXCR4+ epithelial cells to pulmonary fibrosis." (PMID 32843095, 2020). "The first aim of this study was to investigate the utility of circulating CXCR4+ PMBCs as a potential biomarker in idiopathic pulmonary fibrosis (IPF)." (PMID 32843095, 2020). "Xu and colleagues demonstrated that SDF-1 levels and CXCR4pos cells are increased in patients with idiopathic pulmonary fibrosis and antagonism of CXCR4, attenuates bleomycin-induced lung fibrosis." (PMID 31718614, 2019). "Previous research has reported that CXCR4 antagonist AMD3100 prevented bleomycin-induced murine pulmonary fibrosis by inhibiting the fibrocyte mobilization to the injured lung." (PMID 31501415, 2019). "Previous studies have reported that the CXCR4 antagonist prevented bleomycin-induced murine pulmonary fibrosis by inhibiting the recruitment and migration of bone marrow-derived fibrocytes to the injured lungs." (PMID 31501415, 2019). "In this study, we demonstrated that the number of CD41+ megakaryocytes increased in bleomycin (BLM)-induced lung fibrosis tissues through the Chemokine (CXCmotif) ligand 12/Chemokine receptor 4 (CXCL12/CXCR4) axis." (PMID 31501415, 2019). "In idiopathic pulmonary fibrosis, the interaction of CXCL12 and CXC receptor 4 (CXCR4) plays a critical role in lung fibrosis." (PMID 29499695, 2018). "A previous study demonstrated that AMD3100 (a CXCR4 antagonist) attenuates bleomycin-produced lung fibrosis in mice." (PMID 29499695, 2018). "Several reports showed that treatment of mice with a CXCL12 antibody or CXCR4 antagonist (AMD3100) diminished bleomycin-stimulated lung fibrosis." (PMID 29499695, 2018). "Here, anti-CXCR3 and anti-CXCR4 ab levels are shown to be very good markers of predicting lung fibrosis and are, therefore, candidates to stratify patients for disease progression, e.g., in clinical studies." (PMID 29566745, 2018). "CXCL12 acts on CXC receptor 4 (CXCR4) receptors to promote fibrocyte homing to the lungs and further lead to pulmonary fibrosis." (PMID 29499695, 2018). "Frequencies and median fluorescence intensities (MFI) of CXCR3+ and CXCR4+ PBMCs were lower in SSc patients compared with HD and correlated with the severity of skin and lung fibrosis." (PMID 29566745, 2018). "Collectively, these results suggest that targeting CXCR4 signaling via AD-114-PA600-6H or AMD3100 effectively ameliorated fibrotic lung remodeling in a pre-clinical murine model of lung fibrosis." (PMID 29453386, 2018). "Recent studies established that CXCL12/CXCR4 axis characterizes the key pathway in regulation of fibrocyte migration and participates in pulmonary fibrosis." (PMID 29499695, 2018). "Our team has previously investigated the role of SDF1/CXCR4 axis in migration of BM-MSCs in Idiopathic Pulmonary Fibrosis and Rheumatoid Arthritis with Usual Interstitial Pneumonia." (PMID 28804668, 2017). "Based on these and other observations, it has been proposed that CXCL12 chemoattracts BMDMSC and circulating fibrocytes to the lung via CXCR4/CXCL12 signaling during lung fibrosis." (PMID 26998906, 2016). "In a mouse model of bleomycin-induced lung injury, circulating CXCR4+ fibrocytes infiltrated and contributed to lung fibrosis after homing in response to the lung-plasma CXCL12 gradient, suggesting an active traffic through this pathway." (PMID 27309347, 2016). "Under hypoxia, the SDF-1/CXCR4 axis accelerates extracellular matrix deposition, resulting in the development and progression of idiopathic pulmonary fibrosis." (PMID 24661402, 2014). "The fibrocytes expressing CXCR4 were collected in the context of mouse and human pulmonary fibrosis." (PMID 24505417, 2014).
pulmonary fibrosis (continued). "Many studies have shown that the SDF-1/CXCR4 biological axis plays an important role in the pathogenesis of idiopathic pulmonary fibrosis." (PMID 24661402, 2014). "CXCL12 (stromal cell-derived factor-1, SDF-1) is a potent chemokine for homing of CXCR4+ fibrocytes to injury sites of lung tissue, which contributes to pulmonary fibrosis." (PMID 25121739, 2014). "Various studies have shown that CXCR4 inhibition reduces lung fibrosis via reduced fibrocyte migration." (PMID 24587052, 2014). "Previous reports indicated a critical role of the CXCL12/CXCR4 axis in fibrocyte migration in the lungs and its contribution to pulmonary fibrosis." (PMID 25121739, 2014). "A large body of evidence has accumulated which suggests that CXCL12 and its receptor, CXCR4, participate in pulmonary fibrosis." (PMID 25121739, 2014). "For example, a recent study indicated that bleomycin-induced pulmonary fibrosis in mice is blocked by the CXCR4 antagonist, AMD3100." (PMID 25121739, 2014). "CXCL12 is a ligand of the chemokine receptor, CXCR4, and plays an important role in pulmonary fibrosis." (PMID 25121739, 2014). "Further, Ccl-12 and Cxcr-4 that were both shown to be involved in pulmonary fibrosis, Ccl-3 which has been described to be important in systemic sclerosis, and Ccr-2 that is associated with allograft fibrosis, were overexpressed." (PMID 24143891, 2013). "Consistent with this, pharmacological antagonism of CXCR4 also results in reduced lung fibrocyte numbers and pulmonary fibrosis in response to bleomycin." (PMID 23259468, 2012). "The concept of fibrocyte CXCR4 regulation as a therapeutic target in pulmonary fibrosis has been recently reported by several groups using the bleomycin-induced model of lung fibrosis." (PMID 21219601, 2011). "Using the Robust Cell Type Decomposition algorithm to deconvolve spatial transcriptomic data, we identified Cxcr4+ macrophages and Cxcl12+ fibroblasts as central drivers of pulmonary fibrosis progression, revealing a distinct spatial co-localisation pattern between these cell populations." (PMID 42204838, 2026). "CXCR4 inhibition has been proposed to have beneficial effects on both the prevention and management of acute respiratory distress syndrome and related cytokine storms, pulmonary fibrosis, and imbalanced angiogenesis in SARS-CoV-2-infected lungs." (PMID 39407172, 2024). "We sought to test the hypothesis that short-term treatment with sirolimus reduces the concentration of CXCR4+ circulating fibrocytes in patients with idiopathic pulmonary fibrosis (IPF)." (PMID 36853800, 2023). "CXCR4/CXCL12 axis which is involved in the control of lung fibroblast activity has been shown to be required for fibrocyte participation in the pathogenesis of lung fibrosis." (PMID 36164329, 2022). "Furthermore, it had been published that the CXCL14/CXCR4 chemokine axis is involved in the progression and/or activation of fibroblasts during initiation of pulmonary fibrosis in the lung." (PMID 33670189, 2021). "In the lung, CXCR4 expression is thought to contribute to the cellular trafficking from the vessels into the interstitium and contribute to a number of fibrotic disorders including asthma and pulmonary fibrosis." (PMID 32843095, 2020). "Our results provided the first evidence that G-CSF could promote the migration of BMSCs to damaged lung tissue through upregulating the expression of CXCR4 on BMSCs, which could effectively alleviate pulmonary fibrosis." (PMID 32601321, 2020). "In addition, pharmacological inhibition of the CXCL12/CXCR4 axis with WZ811 significantly attenuated lung fibrosis after BLM challenge reflected by morphological changes, ɑ-SMA, Col III, and TGF-β1 levels, and HYP content." (PMID 31501415, 2019). "Thus, our research suggests that pharmacological blocking of the CXCL12/CXCR4 axis can reduce megakaryocyte chemotaxis to damaged lung tissues, ultimately partially mitigating lung fibrosis." (PMID 31501415, 2019).